HDAC1 (histone deacetylase 1)
Diseases named in the same sentence as HDAC1 in open-access papers (continued):
Sharing a sentence is not in itself a finding about the gene and the disease.
infection (continued). "pUL38 was coprecipitated with an HDAC1-specific antibody from whole cell lysates after infection with wild-type virus but not pUL29/28-deficient viruses." (PMID 20585571, 2010). "Also, the identity of host proteins associated with HDAC1 during M. tuberculosis infection and their role in the progress of infection/pathogenesis are also not known." (PMID 33627504, 2021). "To demonstrate the IAV-induced STAT3 nuclear translocation and the role of HDAC1 and HDAC2 in such translocation, we used an early infection timepoint, 6 h." (PMID 39861822, 2024). "Following infection with PA14, mvfR, or pqsA, the transcript levels of Scd1 were significantly higher in HDAC1 KD cells than in corresponding infected control macrophage cells." (PMID 37010415, 2023). "Transfections of histone deacetylase 1 (HDAC1) expression vectors and/or specific siRNA were conducted in HeLa-CD4 and 293 T cells followed by infection with fully infectious NL4–3 and luciferase-expressing pseudotyped viruses or by proviral DNA transfection." (PMID 31744547, 2019). "To delineate the transcript level of HDACs during MTB infection, we measured the levels of HDAC1 and HDAC2 expression in human macrophages following infection." (PMID 26697414, 2015). "We observed that following infection with live MTB H37Rv at 24 h PI, there was an increased recruitment of HDAC1 to the promoter of IL-12B gene." (PMID 26697414, 2015). "We measured CX3CL1 mRNA levels in cells following infection in the presence of HDAC inhibitors, TSA (for HDAC1/2) and EX527 (for HDAC3 type Sirt1)." (PMID 23724129, 2013). "We conclude that HDAC1 and a second component of the NuRD complex, MTA2, interact either directly or indirectly with both HCMV pUL29/28 and pUL38 proteins during infection." (PMID 20585571, 2010). "Histone deacetylase 1 (HDAC1) expression, activity and binding to the defense gene promoters significantly increased during infection, which resulted in decreased histone H3 acetylation in infected cells." (PMID 19543390, 2009). "Following reconstitution of irradiated recipients (CD45.1+) and subsequent infection, we observed reduced frequencies of the early Texeff-like cell subset within the reconstituted CD45.2+ HDAC1-deficient but not CD45.2+ WT and CD45.1+ compartment." (PMID 40464916, 2025). "Likewise, IAV also antagonizes HDAC1 and HDAC2, and their levels are decreased in infected cells at the later infection timepoints." (PMID 39861822, 2024). "We found that the host proteins HDAC1 and CAD play a key role in the FMDV infection process." (PMID 37162335, 2023). "HDAC1 was significantly upregulated by the overexpression plasmid; however, the RNA level of FMDV 3D protein did not increase with increasing duration of infection in the HDAC1-overexpressing cells." (PMID 37162335, 2023). "Thus, we found significant interactions of diet and infection for several genes, especially those related to the mucosal barrier, such as DCLK1, HDAC9, IL13RA1, MUC2 and HDAC1 (Fold change 2.5, 1.9, 1.3, 1.3 and − 1.2, respectively)." (PMID 38081984, 2023). "The infection with AIEC bacteria did neither induce significant modulations of HDAC1 and HDAC5 expression nor modification of H3 global acetylation in colonic mucosa of Chow-fed mice." (PMID 36175163, 2022). "Interestingly, Miller and colleagues showed that H3K56 deacetylation is also a downstream DNA damage responsive PTM carried out by HDAC1, and our and other groups previously demonstrated that HSV-1 induces DNA damage during productive infection." (PMID 34208020, 2021). "The specific regulation of this HDAC was confirmed by a lack of any effect of infection with either virus on HDAC1." (PMID 31067474, 2019). "We therefore downregulated the expression of HDAC1 in U251 and T98G cells by infection with pLVTHM-shRNA negative control (NC) or pLVTHM-HDAC1-shRNA in U251 and T98G cells." (PMID 28624794, 2017).
infection (continued). "Since PML interacted with STAT1, STAT2, HDAC1, and HDAC2, we investigated whether IE1 simultaneously interacts with PML, STAT1, STAT2, and HDACs during infection." (PMID 25812002, 2015). "To investigate whether HDAC1 expression was dependent on the strength of infection, we infected macrophages with live MTB H37Rv at different MOI, and HDAC1 was quantified at 24 h PI." (PMID 26697414, 2015). "Our experiments with primary macrophage cells further prove that the increased level of HDAC1 observed is due to the infection by virulent M. tuberculosis irrespective of the cells used." (PMID 26697414, 2015). "Since we observed a direct correlation between infection with live, virulent MTB and the levels of HDAC1 in macrophages, we wished to test whether HDAC1 plays a role in the survival of the bacteria inside the macrophages." (PMID 26697414, 2015). "To distinguish between necrosis by viral replication and apoptosis by repression of HDAC1 and overexpression of p73, we monitored the changes in expression of the pro-apoptotic genes Apaf-1, Bax, Bim, and PUMA 48 hours after infection of SK-Mel-147 cells with the oncolytic viruses by real-time PCR." (PMID 25071017, 2014). "In the absence of infection, HDAC1 is observed within distinct nuclear structures in complex with CoREST and LSD1; however, upon HSV-1 infection, the HDAC1/CoREST/LSD1 complex is redistributed to compact structures that also contain the viral protein ICP8." (PMID 23807710, 2013). "It was found that the endogenous HDAC1 mRNA level was decreased in response to infection by 2.77 fold in the presence of G1 miRNAs (including miR-449b) during infection, but not G2 miRNAs." (PMID 24086750, 2013). "To define at which time point upon infection Tex subset composition is altered in the absence of HDAC1, we examined the kinetics of the appearance of CX3CR1+ cells at 48 and 67 h as well as day 5 and 8 p.i. and also determined the activation and expansion of early Tex cells." (PMID 40464916, 2025). "Together, these observations uncover a previously unknown interaction between IFI16 and HDAC1/2 in cells under normal physiological conditions, regardless of their infection status, and propose a potential link between IFI16 and the KSHV latency protein LANA." (PMID 39927772, 2025). "Therefore, the visualization of STAT3 nuclear translocation in the presence or absence of HDAC1 or HDAC2 expression at the 6 h infection timepoint represents its accurate activation window." (PMID 39861822, 2024). "However, such EGFP distribution did not change after the infection and/or the depletion of HDAC1 expression (rows 2–4)." (PMID 39861822, 2024). "Similarly, fluorescence confocal microscopy and quantification of the LC3B punctation showed that punctation was not altered in HDAC1 KD cells following infection or 2-AA exogenous addition compared to wild-type cells (2-fold reduction in LC3B)." (PMID 37010415, 2023). "The infection with LCMV revealed reduced numbers of MHC class I/peptide-gp33 tetramer-positive (tet-gp33+) CD8+ T cells in the absence of HDAC1 correlating with impaired cytokine expression upon re-stimulation of splenocytes and liver cell suspensions in comparison to WT mice." (PMID 25333902, 2014). "Compared to the control cells receiving 2-AA, HDAC1 KD cells showed robust CTx-B staining, which was not affected by 2-AA addition or PA14 infection." (PMID 37010415, 2023). "In co-IP assays performed at 8 h after infection, PML was found to interact with STAT1, STAT2, HDAC1, and HDAC2 in UV-HCMV-infected cells but not in uninfected cells." (PMID 25812002, 2015). "This was confirmed for HDAC1 and HDAC8 by inducing infection without the need for the virus to undergo endocytosis." (PMID 22046129, 2011).
infection (continued). "Results showed a significant increase in Sin3 and HDAC1 levels in HSV-1 infected neurons 24 h p.r. with respect to matched CTRL, whereas no significant changes were detected 24 h after the primary infection (24 h p.r.: Sin3, * p = 0.017 vs. CTRL; HDAC1, * p = 0.035 vs. CTRL)." (PMID 34208020, 2021). "HeLa-CD4 cells transfected with HDAC1 siRNA (Hs_HDAC1_5) or a non-related control siRNA (GFP-22 siRNA) were infected with HIV-1 NL4–3 and replication was monitored for 8 days by quantification of the p24 viral protein in cell supernatants at day 1, 2, 3, 5 and 8 post-infection (pi)." (PMID 31744547, 2019). "Mock infection and treatments of cells with non-oncolytic Ad-derived vectors either without a transgene (Ad.Empty), or vectors able to transduce the cells either with an shRNA against GFP (Ad.shGFP), an shRNA against HDAC1 (Ad.shHDAC1) or TP73 (Ad.p73) were used as expression controls." (PMID 25071017, 2014).
neurodegenerative disease (12 papers, 2013 to 2025). A disorder of the central nervous system characterized by gradual and progressive loss of neural tissue and neurologic function. "HDAC1 belongs to Class I of HDACs and plays a critical role in gene regulation and is directly associated with carcinogenesis and neurodegenerative diseases." (PMID 39752394, 2025). "Intriguingly, HDAC1 overexpression is linked with neurodegenerative diseases, and the inhibition of HDAC class I proteins with an HDAC inhibitor was indicated to be potentially neuroprotective." (PMID 34115777, 2021). "This aspect is particularly relevant given HDAC1’s role in neurodegenerative diseases, suggesting potential applicability beyond oncology." (PMID 39752394, 2025). "Histone deacetylase 1 (HDAC1) is involved in DNA repair and neuroprotection in numerous neurodegenerative diseases." (PMID 32449313, 2020). "In this study, we confirmed that GLE1 knock-down reduces the cytoplasmic mRNA expression of some genes, like FUS and HDAC1, which participate in neurodegenerative disease." (PMID 29746542, 2018). "The interplay between HDACs 1 and 3 in neurodegenerative diseases is well established as well as the interaction between HDAC1 and HDAC3 in neuronal cells [see for example Ref." (PMID 25798128, 2015). "Our findings indicate a previously unknown mechanism whereby HDAC1 deregulation in TDP‐43 proteinopathies leads to DNA damage and substantial cell cycle deregulation, which results in neuronal loss and brain degeneration." (PMID 32449313, 2020). "However, the role of HDAC1 in neurodegenerative diseases remains unclear." (PMID 34381129, 2021). "Here the authors reveal a role for HDAC1 in stimulating OGG1 activity to alleviate 8-oxoG lesions with implications in the aging brain and neurodegenerative diseases." (PMID 32424276, 2020). "Our findings link HDAC1 and OGG1 to oxidative DNA damage, neuronal gene expression, synaptic plasticity, and cognitive performance in brain aging and neurodegenerative disease, and highlight the therapeutic potential of pharmacological HDAC1 activation in aging and neurological disorders." (PMID 32424276, 2020).
kidney (6 papers, 2008 to 2022). "Plasma BUN was elevated in the male iHoxb7 Hdac1/2KO mice consistent with the kidney damage observed." (PMID 32673289, 2020). "Decreased nuclear WTAP in NASH leads to the impairment of the WTAP/HDAC1 axis and increases the transcription of Igfbp1, Cd36 and Ccl2, which further increases lipolysis in WAT, hepatic FFA uptake and liver inflammation, respectively, finally causing NASH pathogenesis." (PMID 35927268, 2022). "Plasma electrolytes were similar between female control and iHoxb7 Hdac1/2KO, but the KO mice had an elevated BUN consistent with the kidney damage observed." (PMID 32673289, 2020).
hematological malignancies (5 papers, 2016 to 2023). "This provides the rationale for utilization of selective Hdac1 and Hdac2 inhibitors in the treatment of hematological malignancies." (PMID 27886239, 2016). "MS-27528–31 (HDAC1 selective) and MGCD010332–36 (HDAC1, 2 selective) are two benzamide HDACIs designed for the treatment of both hematologic malignancies and solid cancers, which are currently in clinical trial as mono therapies or in combination with other drugs." (PMID 29616828, 2018). "The two histone deacetylases (Hdacs), Hdac1 and Hdac2, are erasers of acetylation marks on histone tails, and are important regulators of gene expression that were shown to play important roles in hematological malignancies." (PMID 27886239, 2016).
cardiovascular diseases (4 papers, 2019 to 2025). "These various roles underscore HDAC1's potential as a therapeutic target in cardiovascular disease and regeneration." (PMID 40660005, 2025). "In summary HDAC1 and HDAC3 are crucial in cardiovascular diseases." (PMID 40660005, 2025).
hematologic cancers (4 papers, 2021 to 2025). "In particular, given the association of HDAC1 and HDAC6 with the progression of AML and CLL – two hematologic cancers for which venetoclax has already received FDA approval – we elected to focus on achieving HDAC1 and HDAC6 selectivity in our dual BCL‐2/HDAC inhibitors." (PMID 40370107, 2025).
neurological diseases (4 papers, 2017 to 2023). "Our results showed HDAC1 is necessary for hippocampal neuronal differentiation in vitro, but more analysis is needed to clarify the in vivo role of HDAC1 during adult hippocampal neurogenesis, and to find more specific HDAC treatments for neurological diseases." (PMID 35095417, 2021). "Understanding the role of HDAC1 may lead to ways to control stem cell proliferation and neuronal regeneration in the adult hippocampus, and to more specific HDAC therapeutics for neurological disorders." (PMID 35095417, 2021).
adenocarcinoma (3 papers, 2008 to 2024). A common cancer characterized by the presence of malignant glandular cells. "Strong nuclear HDAC1, HDAC2 and HDAC3 immunoreactivity was seen in most adenocarcinomas." (PMID 18212746, 2008).
brain disorder (3 papers, 2013 to 2021). A disease affecting the brain or part of the brain. "Histone deacetylase 1 (HDAC1) plays important roles in self-renewal of stem cells as well as the recovery of brain disorders." (PMID 30662396, 2018). "This study herein provides evidence that a specific HDAC1 activator that solves these challenges will potentially extend the therapeutic window and possibly lead to the clinical application of the HDAC-based therapeutic approach in treating brain diseases." (PMID 34638996, 2021).
immune dysfunction (3 papers, 2022 to 2023). "We demonstrate that hypoxia-induced factor 1α (HIF1α) interaction with HDAC1 and concurrent PRC2 dependency causes chromatin remolding resulting in epigenetic suppression of effector genes and subsequent immune dysfunction." (PMID 35840558, 2022). "HIF‐1α interacts with histone deacetylase 1 (HDAC1) and simultaneously relies on polycomb repressive complex 2 protein with histone methyltransferase activity to induce chromatin remodeling, thereby leading to immune dysfunction." (PMID 36703877, 2023). "After Hg exposure, the SMAD4 and HDAC1 were down-regulated and DUOX was up-regulated in our study; these results suggest that Hg exposure could weaken the immune response and ability, as well as induce immune diseases." (PMID 36290667, 2022).
peripheral neuropathy (3 papers, 2022 to 2024). A disorder affecting the peripheral nervous system. "At analgesic doses, SUM52 reduced the spinal overexpression of HDAC1 and BRD4 induced by the peripheral neuropathy." (PMID 35501470, 2022). "As opposed to the RNAseq study, we identified HDAC1, a class I HDACs, was transiently up-regulated in DRG neuronal nuclei at mRNA and protein levels in the oxaliplatin-induced peripheral neuropathy model." (PMID 39542827, 2024).
inflammation (2 papers, 2022 to 2024). Aberrant reaction of the microcirculation characterized by movement of fluid and leukocytes from the blood into extravascular tissues. "Furthermore, the ability of Parabacteroides to improve COPD-associated lung inflammation through the lung-gut axis may be related to its regulation of the key target genes ReLA and HDAC1, thereby reducing the production of NETs in the lungs." (PMID 39629210, 2024). "In conclusion, our results suggest that RAGE modulates HDAC1 expression via the PI3K/AKT pathway, and that inhibition of HDAC prevents TDI-induced airway inflammation." (PMID 35148729, 2022).
myopathy (2 papers, 2012 to 2013). A disease of the muscle in which the muscle fibers do not function properly. "HDAC1/2 knockout mice surviving postnatally develop a progressive myopathy characterized by autophagy impairment." (PMID 24710479, 2012). "Moreover, feeding HDAC1/2 knockout mice with a high-fat diet releases the block in autophagy and prevents myopathy." (PMID 24710479, 2012). "Muscle-specific ablation of both HDAC1 and HDAC2 results in partial perinatal lethality, while those HDAC1/2 knockout mice that survive develop a progressive myopathy characterized by impaired autophagy." (PMID 23665154, 2013).
head and neck tumors (1 paper, 2015). "Our results show that HDAC1 expression is significantly higher (Mann-Whitney test; p = 0.0262) in head and neck tumors as compared to adjacent normal control tissues." (PMID 26000099, 2015).
kidney diseases (1 paper, 2023). "VPA (inhibitor of HDAC1 and HDAC2), which was used in the clinic for many years, has been found to play a protective effect on a variety of kidney diseases." (PMID 37153759, 2023).
psychiatric disorder (1 paper, 2022). A disorder characterized by behavioral and/or psychological abnormalities, often accompanied by physical symptoms. "We further measured the mRNA levels of a number of genes known to be involved in the pathology of psychiatric disorders, including Bdnf, Fosb, Drd1/2, Grik2, Hdac1/9v, and Grin2a/b." (PMID 36582489, 2022).
skin disorder (1 paper, 2023). Any deviation from the normal structure or function of the skin or subcutaneous tissue that is manifested by a characteristic set of symptoms and signs. "Taken together, downregulating the expression of HDAC1 may contribute to the amelioration of skin disorders in AD." (PMID 37330465, 2023).
HDAC1 also shares sentences with these, for which no sentence is quoted: squamous cell carcinoma (3 papers); Thrombocytopenia (3); atherosclerotic heart disease (2); benign tumor (2); blood cancers (2); COVID-19 (2); Crohn disease (2); Diabetic Nephropathy (2); gastrointestinal tumors (2); inflammatory bowel disease (2); intrahepatic cholangiocarcinoma (2); Iron deficiency (2); lung disease (2); metabolic disease (2); Myocardial fibrosis (2); obstructive sleep apnea (2); oral squamous cell carcinoma (2); papillary thyroid carcinoma (2); prostate (2); prostate adenocarcinoma (2); Airway obstruction (1); alcoholism (1); allergies (1); alveolar soft part sarcoma (1); Angelman syndrome (1); angioimmunoblastic T-cell lymphoma (1); ankylosing spondylitis (1); atopic dermatitis (1); ATRX syndrome (1); autism spectrum disorder (1).
A further 71 diseases each share a sentence with HDAC1 in 1 paper.